PGR (progesterone receptor)
Diseases named in the same sentence as PGR in open-access papers (continued):
Sharing a sentence is not in itself a finding about the gene and the disease.
gynecologic tumors (2 papers, 2014 to 2021). "The progesterone receptor (PGR) is widely documented as playing a role in various gynecological tumors." (PMID 33782686, 2021). "Patients and Methods: We evaluated anastrozole and everolimus in 55 patients with metastatic estrogen (ER) and/or progesterone receptor (PR)-positive breast and gynecologic tumors." (PMID 24912489, 2014).
brain disorder (1 paper, 2025). A disease affecting the brain or part of the brain. "GR phosphorylation’s (pGR) role in brain disorders and potential therapeutic targets." (PMID 40362450, 2025).
endocrine disorders (1 paper, 2019). "The progesterone receptor (PR) is important therapeutic target for many malignancies and endocrine disorders due to its role in controlling ovulation and pregnancy via the reproductive cycle." (PMID 32039185, 2019).
female reproductive diseases (1 paper, 2016). "Loss of PGR expression or disruption in PGR-mediated signaling is always associated with an unopposed E action/P-resistance in the endometrium that is favorable to cell cycle progression and inflammatory reaction, leading to various female reproductive diseases." (PMID 28239613, 2016).
PGR also shares sentences with these, for which no sentence is quoted: Uterine leiomyoma (16 papers); breast (11); non-small cell lung carcinoma (6); atherosclerosis (3); lobular breast cancer (3); Luminal breast cancer (3); thyroid cancer (3); benign breast disease (2); biliary tract diseases (2); cardiovascular disease (2); erectile dysfunction (2); fatty liver (2); gastric tumor (2); Hyperglycemia (2); hyperlipidemia (2); Insulin resistance (2); kidney tumors (2); liver cancer (2); myocardial infarction (2); neurological diseases (2); non-alcoholic fatty liver disease (2); ovarian clear cell cancer (2); polycystic ovary syndrome (2); rectal cancer (2); renal cell carcinoma (2); scirrhous carcinoma (2); type 2 diabetes (2); urothelial bladder cancer (2); adenomyoma (1); adolescent idiopathic scoliosis (1).
A further 107 diseases each share a sentence with PGR in 1 paper.